ANTXR2 (ANTXR cell adhesion molecule 2)
Description:
Necessary for cellular interactions with laminin and the extracellular matrix. (Microbial infection) Receptor for the protective antigen (PA) of B.anthracis. Binding of PA leads to heptamerization of the receptor-PA complex. Upon binding of the PA of B.anthracis, the complex moves to glycosphingolipid-rich lipid rafts, where it is internalized via a clathrin-dependent pathway. In the endosomal membrane, at pH under 7, the complex then rearranges and forms a pore allowing the other components of anthrax toxin to escape to the cytoplasm.
Synonyms: CMG-2; CMG2; FLJ31074; HFS; ISH; JHF
Tractability: Small molecule: a high-quality ligand is known. Antibody: UniProt places it where antibodies can reach, with high confidence; its Gene Ontology location is reachable by antibodies, with high confidence; UniProt predicts a signal peptide or a membrane-spanning region. PROTAC: ubiquitination databases record sites on it; its protein half-life has been measured; a small molecule that binds it is known.
Gene: Protein-coding gene on chromosome 4 (79,901,146 to 80,125,454, reverse strand). Ensembl gene ENSG00000163297.
Subcellular location: Cell membrane (Isoform 1); Endoplasmic reticulum membrane (Isoform 2); Secreted (Isoform 3)
Pathways (Reactome):
Disease: Uptake and function of anthrax toxins
Gene Ontology:
Molecular function: protein binding; transmembrane signaling receptor activity; signaling receptor activity
Cellular component: endoplasmic reticulum membrane; plasma membrane; cell surface; endosome membrane; external side of plasma membrane; extracellular region; membrane
Genetic constraint (gnomAD): Loss-of-function variants: 34 observed, 46.16 expected, observed/expected ratio (o/e) 0.74, 90% interval 0.56 to 0.98. The upper end of that interval is the gene's LOEUF score, 0.98, which puts it in group 4 of 6, group 1 being the genes least tolerant of losing a copy. Missense variants: 516 observed, 476.5 expected, observed/expected ratio (o/e) 1.08, 90% interval 1.01 to 1.16. Synonymous variants: 192 observed, 160.72 expected, observed/expected ratio (o/e) 1.19, 90% interval 1.06 to 1.35.
Gene-disease validity (ClinGen):
ClinGen rates the evidence that ANTXR2 causes each of these diseases.
hyaline fibromatosis syndrome (autosomal recessive): Definitive.
Homologues: Orthologues: chimpanzee ANTXR2 (99% identical), macaque ANTXR2 (97% identical), pig ANTXR2 (92% identical), dog ANTXR2 (87% identical), guinea pig ANTXR2 (87% identical), rabbit ANTXR2 (86% identical), rat Antxr2 (85% identical), mouse Antxr2 (83% identical), tropical clawed frog antxr2 (61% identical), zebrafish antxr2a (59% identical), zebrafish antxr2b (58% identical). Paralogues in human: ANTXR1 (55% identical), ANTXRL (33% identical).